AGRP (agouti related neuropeptide)
Diseases named in the same sentence as AGRP in open-access papers (continued):
Sharing a sentence is not in itself a finding about the gene and the disease.
Anxiety (continued). "Motivational state competition following the activation of AgRP/NPY neurons could be instrumental for suppressing fear and anxiety in the presence of food, conceivably by those AgRP/NPY projections directly targeting BNST, CeM, and PVT148." (PMID 31271235, 2019). "Given that we did not observe a general increase in anxiety-related behaviors across tests in the current study, the relationship of the changes in AgRP-IR and αMSH-IR with anxiety-related behaviors is unclear." (PMID 30655577, 2019). "The linear regression model found AgRP gene expression in hippocampus to be a negative predictor of the anxiety index." (PMID 30233288, 2018). "Interestingly, inhibition of AgRP neurons decreased the center distance and center time in the OF test, and the number of entries and time spent in the open arms in the EPM test, indicating increased anxiety-like behaviors." (PMID 36641530, 2023). "Thus, during hunger, NPY originating from arcuate AgRP/NPY neurons may not only increase food intake, but also suppress anxiety‐ and fear‐related behavior by Y2R‐mediated suppression of specific BNST afferents/efferents." (PMID 31271235, 2019). "Indeed, activation of AgRP neurons promotes food intake when food is available but shifts energy metabolism and induces behavioral changes, including driving other motivated goal-directed behaviors and reducing anxiety-like behaviors in the absence of food." (PMID 40760098, 2025). "Thus, in that case, it is possible that the degree of stimulation in AgRP neurons may not be enough to change anxiety-related behaviors in unstressed mice." (PMID 39872511, 2023). "However, the role of AgRP neurons in the comorbidity of anxiety and colitis has not been reported." (PMID 36641530, 2023).
Insulin resistance (28 papers, 2009 to 2025). Increased resistance towards insulin, that is, diminished effectiveness of insulin in reducing blood glucose levels. "Acute optogenetic or chemogenetic activation of AgRP neurons resulted in systemic insulin resistance, partially caused by reduced glucose uptake in BAT18,22." (PMID 38378998, 2024). "mTOR-S6K1-mediated phosphorylation of IRS-1, and degradation of IRS-1 and InsR via the proteasomal or lysosomal pathway, respectively, were implicated in the mechanism of insulin-induced insulin resistance in these NPY/AgRP-expressing cells." (PMID 34831343, 2021). "Nevertheless, these data collectively demonstrate that NPY deficiency largely abrogated the profound insulin resistance induced by optogenetic stimulation of AgRP neurons." (PMID 31974377, 2020). "We show that deletion of Rps6kb1 in POMC neurons leads to defective regulation of HGP, while deletion in AgRP neurons causes skeletal muscle insulin resistance." (PMID 25865886, 2015). "In addition, recent studies have described that acute activation of AgRP neurons can cause insulin resistance through an impairment of the insulin-stimulated glucose uptake into brown adipose tissue (BAT)." (PMID 32232085, 2018). "Two main populations of neurons, POMC and AgRP, express leptin receptor and insulin receptor, and insulin action in these neurons affected systematic insulin resistance." (PMID 36042571, 2023). "The proinflammatory cytokine tumour necrosis factor alpha (TNFα) also induces insulin resistance in NPY/AgRP neurons." (PMID 34831343, 2021). "Further, we demonstrate that the acute insulin resistance-inducing effect of both chemogenetic and optogenetic AgRP neuron activation strongly depends on NPY signaling." (PMID 31974377, 2020). "Strikingly, selective re-expression of NPY in AgRP neurons in ChR2AgRP; NPYΔ/Δ mice completely restored the induction of insulin resistance upon optogenetic activation of AgRP neurons during an ITT." (PMID 31974377, 2020). "Selective re-expression of NPY in AgRP neurons attenuates the reduced feeding response and reverses the protection from insulin resistance upon optogenetic activation of AgRP neurons in NPY-deficient mice." (PMID 31974377, 2020). "We had previously demonstrated that the insulin resistance-inducing effect of AgRP neuron activation occurs in part through an acute suppression of sympathetic nerve activation (SNA) of brown adipose tissue (BAT) to induce myostatin expression in BAT7." (PMID 31974377, 2020). "Collectively, these experiments demonstrate that NPY expression in AgRP neurons is required for the acute food intake stimulatory and insulin resistance-inducing effects of optogenetic AgRP neuron activation." (PMID 31974377, 2020). "This analysis revealed that optogenetic stimulation of AgRP neurons in ChR2AgRP; NPYwt/wt mice resulted in the induction of clear insulin resistance during an insulin tolerance test (ITT)." (PMID 31974377, 2020). "Activation of Agouti-Related Peptide (AgRP)-expressing neurons promotes feeding and insulin resistance." (PMID 31974377, 2020). "The differences between the three groups as to the relationships between plasma concentrations of α-MSH and AgRP and anthropometric data, serum biochemical parameters and homeostatic model assessment of insulin resistance were evaluated." (PMID 26758700, 2016). "Interestingly, this attenuation of AgRP neuron-induced insulin resistance following concomitant POMC neuron inhibition occurred independent of a rescue in BAT glucose uptake, arguing that this partial restoration occurs via alternative mechanisms." (PMID 38378998, 2024). "Notably, the concurrent inhibition of POMC neurons with AgRP neuronal activation partially rescued the insulin resistance induced by AgRP neuron activation." (PMID 38378998, 2024).
Insulin resistance (continued). "Notably, we observed an intermediate phenotype in male and female AgRP-Gq;POMC-Gi mice, where simultaneous inhibition of POMC neurons partially rescues the insulin resistance phenotype resulting from activated AgRP neurons." (PMID 38378998, 2024). "Indeed, our study showed that antisense oligonucleotides against AgRP reduced insulin resistance in the Evening group, suggesting that hypothalamic AgRP mediates evening feeding-induced impairment of muscular insulin sensitivity." (PMID 34639172, 2021). "Therefore, to confirm the role of the glucocorticoid-AgRP pathway in insulin resistance observed in the evening feeding schedule group, we established AgRP neuron-specific GR knockout (AgRP-GR-KO) mice using a Cre-loxP system." (PMID 34639172, 2021). "Also, we find clear differences in the magnitude by which optogenetic versus chemogenetic activation of AgRP neurons promotes feeding and induces insulin resistance." (PMID 31974377, 2020). "Acutely stimulating AgRP neurons fails to induce systemic insulin resistance in NPY-deficient mice, while increased locomotor activity upon AgRP neuron stimulation in the absence of food remains unaffected in these animals." (PMID 31974377, 2020). "In addition, a recent study showed that ATF4 deletion in AGRP neurons of the hypothalamus specifically protects against high fat diet induced weight gain and insulin resistance." (PMID 28555094, 2017). "Excess insulin-induced insulin resistance has been demonstrated in several hypothalamic neuronal models, including NPY/AgRP- and POMC-expressing neurons." (PMID 34831343, 2021). "In the hypothalamus, metabolism enhancing TTR expression was upregulated, and the PTPN1 level denoting insulin resistance was downregulated, while NPY, AGRP, POMC, CART levels denoting leptin resistance showed a normalizing trend." (PMID 32943760, 2021). "Activation of AMPK in NPY/AgRP neurons has demonstrated a beneficial role in attenuating elevated NPY levels, and plays a preventative role in the induction of insulin resistance with palmitate treatment." (PMID 27893782, 2016). "After omentectomy, plasma leptin, insulin, NPY, AGRP, and PMCH levels decreased, which may result a decrease in leptin and insulin resistance." (PMID 29367725, 2018). "Therefore, modulation of insulin sensitivity through the opposing actions of AgRP activation and POMC inhibition may converge in the liver to counteract the development of systemic insulin resistance." (PMID 38378998, 2024). "Nevertheless, these studies had not investigated, whether the insulin resistance regulatory role of AgRP neuron activation may depend on functional NPY expression in these neurons." (PMID 31974377, 2020). "However, we could not observe the target brain site of AgRP in Evening feeding-induced insulin resistance." (PMID 34639172, 2021). "However, in the present study we have selectively activated AgRP neurons through complementary chemogenetic and optogenetic approaches and detected changes in AgRP-driven food intake and insulin resistance, which we did not detect in the respective NPY proficient and deficient control groups." (PMID 31974377, 2020).
diabetes (14 papers, 2012 to 2026). "The current work was undertaken to investigate neural mechanisms underlying diabetes pathogenesis: namely, the contribution made by excessive activity of hypothalamic AgRP neurons." (PMID 40371641, 2025). "Our finding that in diabetic Lepob/ob mice, hyperglycemia is normalized by AgRP neuron inactivation identifies these neurons as key drivers of their diabetes." (PMID 40371641, 2025). "Since these neurons are hyperactive in Lepob/ob mice and other rodent diabetes models, we conclude that excessive AgRP neuron activity is a key driver of the diabetes phenotype of these animals." (PMID 40371641, 2025). "Conversely, leptin-deficient states (including fasting as well as most forms of diabetes) are characterized by hyperactive AgRP neurons while POMC neurons are inhibited." (PMID 40371641, 2025). "Collectively, it is suggested that NPY/AgRP neurons are more susceptible to l-lactate than the POMC neurons in the hypothalamic ARC, conditions that can be associated with diabetes-induced alterations in feeding behavior." (PMID 33219201, 2020). "Intravitreal injection of PG20N (MC5 antagonist) and AGRP (MC1 antagonist) worsened the retinal injury with evident changes already after 8 weeks after induction of diabetes." (PMID 26949291, 2016). "In support of this hypothesis, we report that permanent AgRP neuron inactivation recapitulates the sustained diabetes remission induced by icv FGF1 in Lepob/ob mice." (PMID 40371641, 2025). "We therefore sought to determine whether FGF1 inhibits NPY/AgRP neurons and, if so, whether this inhibitory effect is sufficiently durable to offer a feasible explanation for sustained diabetes remission induced by central administration of FGF1." (PMID 35917179, 2022). "The remarkably long-lived duration of this inhibitory effect is compatible with a role for reduced NPY/AgRP neuron activity in the effect of FGF1 to induce sustained diabetes remission in Lepob/ob mice, although additional studies are needed to test this hypothesis directly." (PMID 35917179, 2022). "Discussion of the role played by AgRP neurons in diabetes pathogenesis would be incomplete without acknowledging the 2 additional signaling molecules — neuropeptide Y (NPY) and GABA — that are expressed by and synaptically released from these neurons." (PMID 40371641, 2025). "Because elevated hypothalamic Agrp and Npy mRNA levels are a characteristic finding in rodent models of diabetes, we wondered whether NPY/AgRP neuron inhibition might be a target for the antidiabetic action of FGF1 in the MBH." (PMID 35917179, 2022). "Interestingly, icv leptin administration also normalizes excessive glucagon secretion and HPA axis activity in uncontrolled diabetes, whereas icv FGF1 injection does not — and yet, both appear to inhibit AgRP neurons, activate POMC neurons, and thereby increase net melanocortin signaling." (PMID 40371641, 2025).
Glucose intolerance (13 papers, 2012 to 2025). Glucose intolerance (GI) can be defined as dysglycemia that comprises both prediabetes and diabetes. "Our findings are generally consistent with previous studies demonstrating that maternal obesity causes lifelong weight gain and glucose intolerance associated with disruption in AgRP/NPY and POMC axonal projections during adulthood." (PMID 32163401, 2020). "Maternal obesity also causes lifelong weight gain and glucose intolerance associated with a disruption in POMC and AgRP axonal projections during adulthood." (PMID 41223213, 2025). "Knockdown of CaSR in adult mice specifically in the hypothalamic arcuate nucleus, where GHRH, POMC and AgRP neurons reside, also resulted in increased body weight, adiposity, leptin resistance, and glucose intolerance, and reduced bone mass." (PMID 40501942, 2025). "In contrast, JNK3 deficiency in AgRP neurons in HFD-fed mice caused increased feeding, increased glucose intolerance, increased blood glucose concentration, increased hypertrophy of white and brown adipocytes, and increased hepatic steatosis compared with control Agrp-cre (AgrpWT) mice." (PMID 26910012, 2016). "Acute activation of the GABAergic AgRP-DMH circuit promoted food intake and glucose intolerance, while activation of post-synaptic MC4R neurons in the DMH elicited exactly opposite phenotypes." (PMID 37043384, 2023).
depression (12 papers, 2018 to 2025). "AGRP neurons have also been implicated in circuitry control of nonfeeding behaviors including those associated with reward, anxiety, compulsiveness, depression, and voluntary exercise." (PMID 36189793, 2022). "The present study establishes that AgRP neurons in the ARC are a key component of the neural circuitry underlying depression-related behaviors." (PMID 33432188, 2021). "Since suppressing AgRP neuron activity increases susceptibility to subthreshold unpredictable stress, we next asked whether stimulating AgRP neurons can reverse depression-related behaviors induced by chronic unpredictable stress." (PMID 33432188, 2021). "Furthermore, we employed a chemogenetic approach to selectively inhibit or activate AgRP neurons and determined how altering AgRP neuron activity affects stress susceptibility and chronic stress-induced depression-related behaviors." (PMID 33432188, 2021). "However, available anatomical evidence suggests that AgRP neurons may functionally interact with the mesolimbic pathway, which has been implicated in depression." (PMID 33432188, 2021). "AGRP, NPY, and GABA can also elicit anxiolytic effects, consistent with the AgRP circuitry in modulation of anxiety, depression, and obsessive–compulsive behaviors." (PMID 37036983, 2023). "For example, activation of POMC neurons promotes stress-induced depression, while activation of AgRP neurons reverses stress-induced depressive behaviors." (PMID 39872511, 2023). "Despite these facts, these results suggest an important role of AgRP neurons in the protective effects of leucine deprivation against CRS-induced depression." (PMID 39872511, 2023). "Previous work has shown that hypothalamic AgRP neurons are involved in the regulation of depression-related behaviors under chronic stress." (PMID 39872511, 2023). "Here, we demonstrate that chronic unpredictable stress, an animal model of depression, decreases spontaneous firing rates, increases firing irregularity and alters the firing properties of AgRP neurons in both male and female mice." (PMID 33432188, 2021). "Our findings suggest that AgRP neurons in the ARC are a key component of neural circuitry involved in mediating depression-related behaviors and that increasing AgRP neuronal activity coule be a novel and effective treatment for depression." (PMID 33432188, 2021). "Conversely, activation of AgRP neurons was able to reverse chronic unpredictable stress-induced depression-related behaviors." (PMID 33432188, 2021). "Because leucine deprivation-induced antidepressant effects under CRS depended on AgRP neural activity, we suspect that leucine deprivation may help prevent depression-like behaviors under CUMS and HFD." (PMID 39872511, 2023). "Though the mechanisms underlying GCN2-mediated regulation of AgRP neuron activity are unknown, we show here for the first time that GCN2 is involved in depression, and thus it might be a potential drug target to treat this condition." (PMID 39872511, 2023). "The melanocortin system, to which AGRP belongs, has also been tied to stress and depression." (PMID 36189793, 2022). "Our observations of the temporal correlation between changes in AgRP neuron activity and behavioral deficits in this model suggest that the reduction of AgRP neuron activity may contribute to the development of depression-related behaviors." (PMID 33432188, 2021). "Our findings suggest that promoting AgRP neuronal activity may lead to a novel and effective treatment for depression." (PMID 33432188, 2021). "As AgRP neurons project to multiple brain regions involved in stress reactivity and reward processing, it is not clear which downstream targets may be contributing to the effects of AgRP neurons on depression-related behaviors." (PMID 33432188, 2021). "Whether these neurons, such as AgRP, are involved in AA regulation of depression is unknown." (PMID 39872511, 2023).
depression (continued). "In conclusion, we found that deprivation of single EAAs, including leucine, has a significant protective effect on CRS-induced depression-like behaviors in mice, and these beneficial effects depend on GCN2 and AgRP neural activity." (PMID 39872511, 2023). "For example, it has been shown that suppressed AgRP neuron activity contributes to chronic unpredictable stress (CUMS)- and high-fat-diet (HFD)-induced depression-related behaviors." (PMID 39872511, 2023). "Future studies will examine whether stimulation or inhibition of AgRP neurons can influence the activity of VTA and BNST neurons in the chronic unpredictable stress model and identify which neuronal populations mediate the effects of AgRP neurons on depression-related behaviors." (PMID 33432188, 2021). "In our study, depression is induced via CRS, which may not change kynurenine levels, and the effect of leucine deprivation is mediated by activating GCN2 signaling in AgRP neurons." (PMID 39872511, 2023).